CD4 (CD4 molecule)
Diseases named in the same sentence as CD4 in open-access papers (continued):
Sharing a sentence is not in itself a finding about the gene and the disease.
tumor (continued). "Combination shIDO-ST treatment with anti-PD-1/CTLA-4 antibodies enhanced tumor growth control, compared to either treatment alone, which was associated with significant intratumoral infiltration by CD8+ and CD4+ T cells." (PMID 33339195, 2020). "A clinicopathological study revealed PD-L1 expression levels in tumor microenvironments compared to levels in tumor cells, demonstrated the correlation between the expression of CD4 and interferon-gamma (IFN-γ), and evaluated prognosis." (PMID 32101576, 2020). "This study showed that tumour grade significantly correlated with dysfunction of both CD4+ and CD8+ TILs and the efficacy of nivolumab treatment." (PMID 32277125, 2020). "The main mechanism of tumor immune evasion is immunosuppression in the tumor microenvironment mediated by CD4+, CD25+, and FoxP3+ cells, regulatory T cells (Tregs) and other types of inhibitory cells." (PMID 32226026, 2020). "CD4+ T-helper cells differentiate in specific cytokine environments and acquire effector functions that are critical for pathogen and tumor immunity, but also participate in allergic and autoimmune inflammation." (PMID 32985505, 2020). "Using group-mode of CIBERSORTx, we estimated CD4-GZMA cell specific gene expression between tumor and normal samples." (PMID 33043022, 2020). "Emerging evidence has shown that higher ratios of CD8+/Foxp3+ and CD8/CD4 are more sensitive indicators of prognosis and for monitoring immune function, even serving as biomarkers to predict tumour relapse and responses to treatment." (PMID 32758195, 2020). "Therapeutic cancer vaccines aim to induce de-novo immune responses against cancer cells by promoting the activation and subsequent expansion of tumor-specific CD8+ or CD4+ T cells, which mediate anti-tumor immunity." (PMID 32532030, 2020). "Our results showed accumulation of Th17 cells among tumor-infiltrating CD4+ lymphocytes (p < 0.001 in relation to PB)." (PMID 32148497, 2020). "The proportion of tumor-reactive CD4+ TILs was on average lower and the differences less pronounced across tumor types." (PMID 33198174, 2020). "Tumor volume of the patient was reduced, importantly, the proportions of functional CD4+ T cells and CD8+ T cells increased and exhausted CD4+ T cells and CD8+ T cells decreased after treatment with Vγ9Vδ2 T cells." (PMID 32413966, 2020). "In BMPR1a cKO tumor bearing spleens, Gr1+ cell, CD4+ T cell, and CD8+ T cell clustering was decreased while the B cell cluster increased." (PMID 32318332, 2020). "Taken together, the data from these independent studies highlight the relevance of the CD4 systemic immunity for anti-tumor immunity and clinical responses to ICI therapies." (PMID 32244396, 2020). "Subgroup 2 expressed slightly more T cells, and subgroup 3 had a relative abundance of memory CD4 T cells, mostly positioned in the stromal area with a low level of tumor infiltration." (PMID 32795913, 2020). "In cancer patients, MHC-II restricted CD4 T cell responses against self-antigens have been detected in the circulation and at the tumor site, and a high density of tumor-infiltrating CD4 T cells correlates with good prognosis in many cancer types." (PMID 32630460, 2020). "Knockouts displayed a lower amount of MDSCs which suppress anti-tumor immunity, but a higher number of CD4+ and CD8+ cells (which correlate with better prognosis)." (PMID 33255584, 2020). "The activation of naive CD4+ T cells by DCs not only releases cytokines (IL-4, IL-12 and IFNγ) within the tumour microenvironment but also facilitates its own (CD4+ T cells) differentiation into Th1 cells." (PMID 32466214, 2020). "Targeting TGFβ and therapies directed toward PD-1/PD-L1 or CTLA-4 amplifies tumor control by enabling a robust T cell response with improved CD4+ and CD8+ T cell activation and CD8+ T cell cytokine and cell killing capacity." (PMID 32849557, 2020).
tumor (continued). "In MHCII+ tumor microenvironments, the infiltration of CD4+ T cells increases and LAG3 (an MHCII inhibitory receptor)-induced TIL expression increases, thereby limiting antigen presentation and promoting resistance to anti-PD-1 therapy." (PMID 32000802, 2020). "Immune cell infiltrates determine prognosis, and high CD4/CD3 ratio and high counts of CD163 positive tumor-associated macrophages determine prognosis." (PMID 32658932, 2020). "In accordance, CD4+ tumor infiltrating lymphocytes (TILs) and CD8+ TILs have been described in advanced metastatic disease with perivascular and peritumoral distribution, respectively." (PMID 32992823, 2020). "For CD4+ T cells, tumor reactivity was detected in three out of four TIL cultures, both before and after cell expansion." (PMID 32127601, 2020). "They then migrate to the lymph nodes, in which the naive T cells are activated to effector T cells (CD8+ and CD4+), and return to the primary tumor and distant metastases owing to the tumor‐homing effect induced by tumor‐specific antigens." (PMID 32832363, 2020). "Additionally, the release of TAAs (tumor-associated antigens) or TSAs (tumor-specific antigens) after tumor cell lysis and the antigen presentation by APCs (antigen-presenting cells) lead to an adaptive immune response and activation of antigen-specific CD4+ and CD8+ T cells." (PMID 32411132, 2020). "During tumor growth, cDC2s were shown to be suppressed in their ability to induce differentiation of antitumor CD4+ T cells." (PMID 32486257, 2020). "Intriguingly, and in contrast to our observations, several recent studies have shown that combined blockade of IL-6 and PD-1/PD-L1 checkpoint molecules promotes tumor infiltration of IFN-γ-producing CD4+ T cells and exerts synergistic antitumor effects." (PMID 32107566, 2020). "Flow cytometry revealed that the combination of the anti–CTLA-4 antibody and Tα1 increased the frequency of CD8+ and CD4+ T cells at the tumor site." (PMID 32817121, 2020). "CD4+ T cells have been reported to contribute to the microenvironment remodeling required for sustained tumor regression." (PMID 33372595, 2020). "Alspach and colleagues confirmed previously published data on the contribution of CD4 T cells recognizing tumor neoepitopes for the efficacy of immunotherapy." (PMID 33329566, 2020). "Subsequent flow cytometry of the immune cell composition of lung tissue samples revealed an increase of cytotoxic CD8+ T cells and a decrease of CD4+ T-helper cells as well as an increase in mature macrophages in response to tumor cell EV." (PMID 32737655, 2020). "The expression of HLA class II, which was more often found on tumor cells in HPV+ OPSCC, is associated with longer OS, DFS and disease specific survival (DSS) in OPSCC, supporting a role for CD4+ T cells in the control of OPSCC." (PMID 33425717, 2020). "In the absence of C3aR signaling, murine B16 melanoma tumor growth is reduced, along with an increased tumor infiltration of CD4+ T cells and neutrophils." (PMID 32733461, 2020). "ATV-NDV strongly augmented a tumor-specific T cell response as a result of CD4+ and CD8+ immune T cell interaction." (PMID 32188078, 2020). "In the HCC tissues, PD-L1 was mainly expressed in the cellular membrane and cytoplasm of tumor cells in a diffuse manner; CD4/CD8, CD276 and SOCS3 protein were also mainly found in the cytoplasm and membrane of tumor cells." (PMID 32742491, 2020). "The population of tumor infiltrating CD4+ effector T cells increased distinctly in DTT-COS1 treatment." (PMID 32423130, 2020). "Further P-gp expression is shown in pro-tumor MΦ2-macrophage phenotype and, anti-tumor NK-cell and Th17/CD4+T cell subsets, thus suggesting an apparently conflicting role of P-gp in tumor immunology." (PMID 32195185, 2020). "Recently, PD-1 + CD4 Tregs in the tumour microenvironment were suggested to induce hyper-progressive disease after anti PD-1 monotherapy." (PMID 32277125, 2020).
tumor (continued). "Among all the CD4+ memory T-cells, more than 70% of the cells exhibited a memory phenotype, and in the tumour positive lymph nodes the frequency of T stem cell memory cells was higher than in tumour negative lymph nodes." (PMID 32370743, 2020). "Further, the amount of CD8+ and CD4+ T cells in the tumor were increased after treatment with PEG2k‐Fmoc‐NLG(L)." (PMID 33304763, 2020). "Combined blockade of IL6 and PD-1/PD-L1 signals increases the expression of T cell-attracting chemokines and facilitates IFN-γ-producing CD4 T cell infiltration into tumor tissues, producing a synergistic anti-tumor effect." (PMID 33344447, 2020). "Both CD8 and CD4 CAR T cells were also more highly activated in the tumor, spleen, and tumor draining lymph node in Reovirus infected animals." (PMID 32581235, 2020). "This study was conducted to examine the role of tumor-redirected MHC class I-restricted CD4+ in comparison to tumor-redirected CD8+ T cells against a STEAP1-derived HLA-A*02:01 restricted peptide." (PMID 32610710, 2020). "Note that TIMER is designed specifically for estimating the abundance of six tumor-infiltrating immune cell types (B cells, CD4 T cells, CD8 T cells, neutrophils, macrophages, and dendritic cells)." (PMID 33253170, 2020). "It has been shown that recruitment of regulatory CD4+ T cells into tumors via secretion of CCL17 by tumor accumulating neutrophils represent a potent mechanism of impairment of local antitumor immunity." (PMID 32813937, 2020). "In a mouse 4T1 model of breast cancer, tumor-evoked Bregs (tBregs) transformed resting CD4+ T cells into Foxp3+ Tregs by secreting TGF-β to promote lung metastases." (PMID 33193391, 2020). "The expansion of Th1-like CD4 T cells following blockage of CTLA-4 improves anti-tumor responses by enhancing CD8 infiltration, cytotoxic CD8 T cells activity, and T cell memory formations." (PMID 32655545, 2020). "In an immunohistochemical (IHC) study of tissue microarray cores from 284 gliomas, the number of CD8+ tumor-infiltrating lymphocytes (TILs) correlated negatively with tumor grade whereas the number of CD4+ TILs displayed a positive correlation." (PMID 33117364, 2020). "A reduced number of CD11b+ and CD115+ cells resulted in an increased number of T cells infiltrating the tumor, a lower number of IL-10-releasing CD4+ T cells and a smaller Treg population." (PMID 32488850, 2020). "TIGIT has been shown to be up-regulated on activated CD4 T cells, including Tregs, natural killer (NK) cells, tumor antigen-specific CD8+ T cells and on NK cells where, when engaged, TIGIT directly inhibits cytotoxicity." (PMID 33117369, 2020). "A CD4+ GrB+, but CD3−, innate subpopulation was also detected both in the circulation and in the tumor microenvironment of relapsed cHL cases, and was associated with a favorable response to nivolumab." (PMID 33327433, 2020). "Tumour regression of cholangiocarcinoma was demonstrated following treatment with TILs highly enriched in neoantigen-specific CD4+ T cells." (PMID 32183246, 2020). "Enhanced the intra-tumoral M1/M2 ratio, the CD8/CD4 ratio in the intracranial GL261 tumor model after RQ treatment were evident." (PMID 32020472, 2020). "An antibody-mediated inhibition of this inhibitory signaling resulted in a restoration of CD8+ and CD4+ tumor-infiltrating lymphocyte proliferation and cytokine production." (PMID 33036244, 2020). "The expression of the PD1 receptor on CD8+ and CD4+ T cells in the splenocytes and single tumor cells was confirmed by flow cytometry." (PMID 32733437, 2020). "Using Lewis lung cancer mice model, intraperitoneal injection of Tan IIA at 15 mg/kg significantly inhibited tumor growth, neovascularization, and Bcl-2 expression and increased the levels of CD4+, CD4+/CD8+, and NK cells." (PMID 32265690, 2020). "Glucocorticoid-induced tumor necrosis factor receptor (GITR) can promote tumor regression by inducing the production of IL-9-producing CD4+ T cells." (PMID 32228589, 2020).
tumor (continued). "HQG treatment increased the numbers of both CD4+ and CD8+T lymphocytes but decreased the ratio of CD4+/CD8+ T cells, which is associated with enhanced adaptive tumor immunity." (PMID 32595757, 2020). "The transfer of MHC class-I-restricted TCRs into CD4+ T cells provides an opportunity to stimulate helper T cells in tumours that lack the expression of MHC class II that is required for stimulation of ‘conventional’ helper T cells." (PMID 32708397, 2020). "As a first step to investigate this possibility, we evaluated the ability of unfractionated tumor CD4+ T cells to induce DCReg from monocytes, in vitro." (PMID 32973804, 2020). "Analysis of IFNγ secretion by either CD4 or CD8 T cells showed increased production with only RX-5902 treatment alone in tumor tissue." (PMID 33148223, 2020). "Among the CD45+ population, CD3+, CD4+, CD8+ T cells, and CD3–CD49b+ NK cells had increased, and tumor infiltrating CD4+ and CD8++T cells produced more IFN-γ in AAV-IL-27 treated tumors." (PMID 32292786, 2020). "Naïve CD4+ T cells encountering tumor antigens presented by APCs can differentiate into different cell subsets including Th1, Th2, Th9, Th17, Th22, and Tregs." (PMID 32499786, 2020). "When CD39 expression was compared on viSNE plots of concatenated files for each tumor type, all tumor samples showed high CD39 expression that mapped to CD4 and CD8 T cells." (PMID 32764562, 2020). "In MB mouse models, disruption of CDK5 expression led to strong tumor rejection mediated by CD4 + T cells, highlighting an important role for CDK5 in immune checkpoint regulation." (PMID 33101383, 2020). "The oxygen-deprived tumor microenvironment (TME) upregulates CD137 expression via the transcription factor HIF-α in CD4+ and CD8+ tumor-infiltrating T lymphocytes." (PMID 33362756, 2020). "The bone marrow of tumor bearing mice exhibited B cell, CD4+ T cell, Cd8+ T cell, Gr1+ cell, and CD11b+ cell clusters." (PMID 32318332, 2020). "Next, matched samples from HPV− HNSCC patients were used to evaluate the frequency of PD-1+CD8+ and PD-1+CD4+ cells in peripheral blood and tumour tissues by flow cytometry." (PMID 32616847, 2020). "Recent studies have shown that the suppression of transforming growth factor-β receptor 2 (TGFBR2) in CD4+ T cells has potent anti-tumor effects." (PMID 33374595, 2020). "In the current study, we aimed to examine the impacts of WW2/WW3 recombinant protein on spleen CD4+CD25+/CD4+ proportion in 4T1 tumor-bearing mice." (PMID 32306719, 2020). "The implication of this finding is that both CD8+ and CD4+ T cells are involved in the T cell attack against the tumor, as we demonstrated for the PDA30364 model." (PMID 32358491, 2020). "The upregulation of SOD3 in the tumor stroma makes the tumor endothelium more permissive to adoptively transferred and endogenous tumor-specific CD4+ and CD8+ T-cells." (PMID 33250894, 2020). "As a result, increased CCR9+CXCR3+CD4+ T lymphocytes were recruited to the tumor microenvironment to augment the effect of anti-PD-1 antibody." (PMID 32817793, 2020). "We found that ~10% of CD8+ and ~5% of CD4+ tumor-infiltrating T cells were able to secrete IFN-γ in untreated control mice." (PMID 32461349, 2020). "This anti-tumor immune response following Aza treatment correlated with significantly increased intratumoral infiltration of CD4+ and CD8+ T cells as well as CD11c+ DC and F4/80+ macrophages." (PMID 32296439, 2020). "For example, cDC2s were found to be important during response to anthracycline chemotherapy, and certain tumor models are responsive to adoptively transferred CD4+ T cells." (PMID 32508825, 2020). "Nevertheless, we observed an antitumor effect of tgCD4 T cells in our in vivo model of local tumor growth control, which is in line with several other reports focusing on the contribution of CD4+ T cells to control s.c.-implanted tumors." (PMID 32610710, 2020).
tumor (continued). "Investigations using human and murine CLL models showed alterations of the immunological synapse between tumor B-cells and CD4+ and CD8+ TLs, primarily due to the disorganization of the TL cytoskeleton through inhibition of TCR components by CLL cells." (PMID 33381116, 2020). "Following GEM treatment, myeloid cells in tumor tissues and in peripheral blood decreased while numbers of CD4+ or CD8+ cells increased suggesting that anti-cancer immunity was enhanced." (PMID 32656079, 2020). "Studies in murine models have shown that effective CD8+ T cell responses against MHC class-II-negative tumours required the ‘helper function’ of CD4+ T cells." (PMID 32708397, 2020). "Within T cells, CD8+ cytotoxic T cells remain the most potent mediators of anti-tumor immunity, and a response directed by either CD4+ T helper 1 (Th1) cells or Th17 cells promote CD8+ effector T cell responses." (PMID 32637408, 2020). "Tumor‐infiltrating CD4+ or CD8+ T cells by tissue microarray‐based immunohistochemistry (IHC) were reported in association with response to neoadjuvant chemotherapy." (PMID 32894006, 2020). "The subsets of CD4+T-helper cells, Th17 and Th1 are known to induce anti-tumor effect through secretion of inflammatory cytotoxic cytokines such as IL-17, IFNγ, TNFα, and granzyme." (PMID 32195185, 2020). "Upon activation, CD8+ T-cells can differentiate into cytotoxic T-cells, which recognize and eliminate virally infected and tumor cells, while CD4+." (PMID 32121315, 2020). "Helper CD4+ T cells also play an important role in the development of anti-tumor immunity by improving clonal expansion of CTLs at the tumor site, preventing activation-induced cell death, and promoting the generation and maintenance of memory CTL." (PMID 32850424, 2020). "The infiltration levels of activated CD4 memory T cells, Tregs, M0 macrophages, M1 macrophages and M2 macrophages in Tumor group were significantly increased compared with those in the Normal group." (PMID 32908454, 2020). "The abundance of immune cells with anti-tumor effects including CD8 T cells, CD4 T cells and M1 macrophages, was high in the low-risk group." (PMID 33005180, 2020). "In this context, IL-1β enhanced CD4+TCRβ+RORγt+ cells producing IL-17, which are responsible for slowing down tumor growth." (PMID 32635472, 2020). "RdB/IL-12/IL-18 also increases the cytokine ratio of Th1/Th2, increases tumor infiltration of CD4+ T, CD8+ T and NK cells, and promotes differentiation of T cells expressing IL-12Rβ2 or IL-18Rα." (PMID 32050597, 2020). "We found that all CXCR family members were significantly correlated with CD8+ T cell, CD4+ T cell, neutrophil, and dendritic cell, which were related to tumor progression, metastasis, or prognosis." (PMID 33324682, 2020). "From functional studies in a tumor model, we concluded that CD4+ T cell help confers upon CTLs the exact properties desired for effective anti-tumor immunity, as defined by Chen and Mellman in “The cancer immunity cycle”." (PMID 33123174, 2020). "The modification of tumor cells by a low dose of NDV was reported to strongly augment a tumor-specific T cell response as a result of CD4+ and CD8+ immune T cell cooperation." (PMID 32155856, 2020). "Expression of IFI44 in GSE8835 was associated with the amount of CD4+ cells and CD8+ cells infiltrating in the tumor section, and 66 genes were distinguished as enriched immune signature genes in IFI44-high expression group in HNSC." (PMID 33123469, 2020). "The amounts of tumor-infiltrating DCs, CD4+ T cells, and CD8+ T cells in lent-miR-138-5p-treated 3LL-bearing C57BL/6 mice were also increased compared with these in the other groups." (PMID 32754587, 2020). "The number of CD4 + cells in primary tumours among rats in the RFA-only and OK-432 groups was also significantly higher than that among rats in the control group (all P < 0.01)." (PMID 32541941, 2020).